HHIPL1 (HHIP like 1)
Synonyms: KIAA1822; UNQ9245
Tractability: Antibody: UniProt places it where antibodies can reach, with high confidence; UniProt predicts a signal peptide or a membrane-spanning region; its Gene Ontology location is reachable by antibodies, with medium confidence.
Gene: Protein-coding gene on chromosome 14 (99,645,129 to 99,680,569, forward strand). Ensembl gene ENSG00000182218.
Subcellular location: Secreted
Gene Ontology:
Cellular component: extracellular region; membrane
Genetic constraint (gnomAD): Loss-of-function variants: 40 observed, 46.65 expected, observed/expected ratio (o/e) 0.86, 90% interval 0.67 to 1.12. The upper end of that interval is the gene's LOEUF score, 1.12, which puts it in group 4 of 6, group 1 being the genes least tolerant of losing a copy. Missense variants: 897 observed, 844.34 expected, observed/expected ratio (o/e) 1.06, 90% interval 1 to 1.12. Synonymous variants: 407 observed, 365.49 expected, observed/expected ratio (o/e) 1.11, 90% interval 1.03 to 1.21.
Homologues: Orthologues: chimpanzee HHIPL1 (98% identical), macaque HHIPL1 (96% identical), dog HHIPL1 (85% identical), mouse Hhipl1 (82% identical), rat Hhipl1 (81% identical), tropical clawed frog hhipl1 (66% identical). Paralogues in human: HHIPL2 (50% identical), HHIP (25% identical).
Diseases named in the same sentence as HHIPL1 in open-access papers:
HHIPL1 is named in the same sentence as 10 diseases in open-access papers, as found by Europe PMC text mining. Sharing a sentence is not in itself a finding about the gene and the disease. The quoted sentences say what the papers report.
atherosclerosis (6 papers, 2017 to 2023). A disease characterized by the build-up of fatty material and calcium deposition in the arterial wall resulting in partial or complete occlusion of the arterial lumen. "HHIPL1 encodes a secreted sonic hedgehog regulator that modulates atherosclerosis-relevant smooth muscle cell phenotypes and promotes atherosclerosis in mice." (PMID 36653562, 2023). "In experimental animal models, HHIPL1 deficiency attenuates the development of atherosclerosis by reducing VSMc proliferation and migration." (PMID 35743896, 2022). "Most strikingly, knockout of Hhipl1 caused a substantial decrease in atherosclerosis on 2 different disease-prone backgrounds." (PMID 31163988, 2019). "Finally, variants in HHIPL1 are associated with myocardial infarction, increased blood pressure and coronary artery disease, probably in part, because smooth muscle cell-derived HHIPL1 enhances atherosclerosis as reported in two hyperlipidemic mouse models." (PMID 34895303, 2021). "In this study, we investigated HHIPL1, an uncharacterized gene at the chromosome 14q32 CAD locus, and showed that it encodes a secreted SHH regulator that modulates atherosclerosis-relevant smooth muscle cell phenotypes." (PMID 31163988, 2019). "Our data strongly support HHIPL1 as the causal gene at the 14q32 CAD locus, link hedgehog signaling to atherosclerosis, and identify HHIPL1 as a potential target for therapeutic intervention." (PMID 31163988, 2019). "Our data clearly demonstrate a role for HHIPL1 in atherosclerosis, with Hhipl1 knockout reducing plaque burden by >50% in 2 different hyperlipidemic mouse models." (PMID 31163988, 2019). "Next, we assessed Hhipl1 levels during atherosclerosis progression by measuring its expression in RNA collected from the aortic arch of Apoe−/− mice between 6 and 48 weeks of age." (PMID 31163988, 2019). "In conclusion, HHIPL1, whose locus is associated with CAD in humans, is a new positive regulator of hedgehog signaling that promotes atherosclerosis in mice." (PMID 31163988, 2019). "This is likely the result of increasing numbers of smooth muscle cells during atherosclerosis progression; however, we cannot exclude Hhipl1 expression also being affected by other factors related to plaque development." (PMID 31163988, 2019). "We investigated the expression of Hhipl1 in a hyperlipidemic mouse atherosclerosis model." (PMID 31163988, 2019). "The function of HHIPL1 and its role in atherosclerosis are unknown." (PMID 31163988, 2019). "The function of HHIPL1 gene and its role in atherosclerosis is not fully understood." (PMID 35743896, 2022).
coronary artery disease (4 papers, 2017 to 2024). "Our study strengthens these findings by revealing rare variants in HHIPL1 associated with coronary artery disease." (PMID 39322779, 2024). "HHIPL1 expression was measured in coronary artery disease–relevant human cells, and protein localization was assessed in wild-type and Apoe−/− (apolipoprotein E deficient) mice." (PMID 31163988, 2019). "Inhibition of HHIPL1 protein function might offer a novel therapeutic strategy for coronary artery disease." (PMID 31163988, 2019).
autoimmune disease (1 paper, 2017). A disorder resulting from loss of function or tissue destruction of an organ or multiple organs, arising from humoral or cellular immune responses of the individual to their own tissue constituents. "For example, the genetic risk variant rs2895811 at HHIPL1 gene showed a significantly stronger association with CVD risk in CD than in the other five autoimmune diseases." (PMID 28982122, 2017).
liver fibrosis (1 paper, 2023). "Finally, the analysis of individual transcripts showed that many putative genes associated with liver fibrosis such as Acta2, Col1a1, Lox and Hhipl1 were upregulated in animals fed with SSD." (PMID 37774007, 2023).
neoplasm (2 papers, 2020). A benign or malignant tissue growth resulting from uncontrolled cell proliferation. "Investigated molecules without connection to common key tumor proteins are GNAS, USP8, USP48, HHIPL1, NNAT, RHOU, C5orf66 and RASSF3, which seem to be more specific biomarkers and therefore should be validated for concordant differences in liquid biopsies." (PMID 32498309, 2020).
HHIPL1 also shares sentences with these, for which no sentence is quoted: basal cell carcinoma (1 paper); cataract (1); chronic obstructive pulmonary disease (1); emphysema (1); myocardial infarction (1).